BRAF (B-Raf proto-oncogene, serine/threonine kinase)
Diseases named in the same sentence as BRAF in open-access papers (continued):
Sharing a sentence is not in itself a finding about the gene and the disease.
thyroid cancer (continued). "Since the MAPK pathway is upregulated in thyroid cancer because of activating BRAF mutations and others, we evaluated the effects of FOXD3 knockdown on ERK1/2." (PMID 28430585, 2017). "BRAF V600E mutations were associated with higher T cell and other immune cell estimates in thyroid cancer." (PMID 28749946, 2017). "In thyroid cancer, Kim identified 56 lncRNAs as potentially thyroid cancer-related genes, and demonstrated that lymph node metastasis of thyroid cancer and BRAF V600E mutation was closely related to LOC100507661." (PMID 28086241, 2017). "Various underlying resistance mechanisms against BRAF inhibitor therapy in thyroid cancer have been investigated in previous studies." (PMID 27880942, 2017). "BRAF mutations were enriched in thyroid cancers with low-level energy metabolism because of the mutual exclusiveness between BRAF and RAS mutations." (PMID 28582771, 2017). "The vast majority of BRAF mutations in thyroid cancers were A→T mutations at nucleotide 1799 of coding sequences." (PMID 28582771, 2017). "BRAF (V600E) mutation causes sustained BRAF kinase activity leading to constitutive activation of MAPK cascade pathway, and BRAF (V600E) mutation bearing thyroid cancer presents aggressive clinicopathologic features." (PMID 27880942, 2017). "The previous study demonstrated differential treatment responses of BRAF inhibition in different types of thyroid cancer harboring BRAF (V600E) mutation." (PMID 27880942, 2017). "In conclusion, our combined data indicate that the expression of autophagy-related proteins in thyroid cancers differs according to the subtype and, among PTCs, the BRAF V600E mutation status." (PMID 28257096, 2017). "Nevertheless, this subject is under debate with other studies linking sub-clonality to early disease stage for BRAF mutation in thyroid cancer and KRAS mutation in pancreatic and colon cancer." (PMID 28501852, 2017). "Previously, the authors have elucidated to a considerable level the causative mechanism underlying acquired resistance to BRAF inhibition in BRAF (V600E) mutant thyroid cancer." (PMID 27880942, 2017). "A phase I study of dabrafenib in combination with lapatinib in BRAF-mutated thyroid cancer had been initiated (NCT01947023)." (PMID 29085335, 2017). "Multiple genetic mutations or alterations are involved in the tumorigenesis of thyroid cancer, BRAF (V600E) mutation being the most common." (PMID 27880942, 2017). "Cell proliferation, cell cycle distribution, induction of apoptosis and EGFR and AKT signaling were evaluated in thyroid carcinoma cell lines bearing the BRAF V600E mutation in response to PLX4032." (PMID 29033690, 2017). "The majority of thyroid carcinomas contain one of a small number of oncogenic driver mutations such as BRAF V600E or an activating mutation in one of the RAS genes." (PMID 28008156, 2017). "The BRAF V600E mutation is the most common mutation in thyroid cancer, particularly in papillary thyroid carcinoma (PTC), and plays an important role in tumorigenesis and progression." (PMID 26857243, 2016). "This is noteworthy because BRAF mutation is recognized as risk factor for thyroid cancer progression and because, so far, KRAS proteins have proved very difficult to be directly targeted." (PMID 27058903, 2016). "Mutations in the TERT promoter, ALK rearrangement, and the BRAF V600E mutation are associated with aggressive clinicopathologic features in thyroid cancers." (PMID 26857243, 2016). "Acquired resistance to BRAF V600E mutation inhibition presents a significant therapeutic challenge in thyroid cancer patients." (PMID 27127178, 2016). "RAS mutations (KRAS, NRAS, and HRAS) are found at a relative low frequency in differentiated thyroid cancers compared with the more common BRAF mutations." (PMID 27127178, 2016).
thyroid cancer (continued). "Previous studies have demonstrated that increased activation of MAPK pathway, which is related with mutations of BRAF gene, is generally found in thyroid cancers." (PMID 26985248, 2016). "We found that TERT promoter mutations are prevalent in aggressive thyroid cancers and are associated with distant metastasis of WDTCs in Korean patients with a high prevalence of the BRAF V600E mutation." (PMID 26857243, 2016). "Recent studies have reported TERT promoter mutations in thyroid cancers; these mutations are particularly prevalent in aggressive thyroid cancers and BRAF mutation-positive PTC." (PMID 27064992, 2016). "We report for the first time the clinical impact of TERT promoter mutations on thyroid cancers that occur in a BRAF V600E prevalent area." (PMID 26857243, 2016). "The most prevalent and studied mutation in thyroid cancer is the T1799A point mutation of the BRAF gene." (PMID 26886957, 2016). "The presence of BRAF mutations is significantly associated with advanced thyroid cancers with metastasis and poor prognoses." (PMID 26830329, 2016). "Thyroid cancers harbor characteristic genetic alterations, including point mutations for proto-oncogenes (BRAF, NRAS, HRAS, KRAS) and chromosomal rearrangements (RET/PTC1, RET/PTC3, PAX8/PPARG), which vary with histologic subtype." (PMID 27871285, 2016). "We aimed to investigate the prevalence of TERT promoter and ALK mutations in thyroid cancer patients with a high prevalence of the BRAF V600E mutation and their potential contribution for the risk stratification of these patients." (PMID 26857243, 2016). "BRAF gene is frequently mutated in a wide range of tumors, particularly in skin cutaneous melanoma and thyroid carcinoma, and activating mutations in BRAF lead to continuous stimulation of the ERK signaling pathway." (PMID 26916442, 2016). "Eleven of 18 BRAFV600E-specific genes were previously reported as related to thyroid cancer, with 6 documented as associated with BRAF mutation (DCSTAMP, MET, FN1, DIO1, EPHA2, and ERBB3)." (PMID 26625260, 2015). "Sixth, since the BRAF mutation is only found in PTCs, the prediction models cannot be applied to other types of thyroid cancers." (PMID 26020381, 2015). "One example for such attempt to use BRAF mutations as a molecular testing is clinical management of thyroid cancer." (PMID 29061943, 2015). "One study examined the presence of BRAF mutations in a cohort of canine thyroid cancers comprising 47 FTC and 16 MTC." (PMID 29061943, 2015). "As nodules with the BRAF mutation are ~100% indicative of thyroid cancers (PTCs), BRAF-mutated thyroid nodules can be treated by total thyroidectomy without necessitating the diagnostic lobectomy." (PMID 29061943, 2015). "In our experimental setting, apoptosis induction and membrane disruption after sorafenib treatment was not significantly influenced by the histological origin of and BRAF mutational status of thyroid carcinoma cells." (PMID 25879531, 2015). "The majority of thyroid carcinomas contain one of a small number of driver mutations, such as BRAF or RAS mutations, gene fusions involving RET, or gene fusions between PAX8 and PPARG." (PMID 26595524, 2015). "PCCL3 cells also have been used to create cell culture models of thyroid carcinomas caused by oncogenic driver mutations in BRAF and RAS, and RET gene fusions." (PMID 26595524, 2015). "In this study we aim to better characterize molecular effects and efficacy of sorafenib against thyroid carcinoma cells with various histological origins and different BRAF mutational status." (PMID 25879531, 2015). "In summary, our results demonstrate that the BRAF- and multikinase inhibitor, sorafenib, exhibited various inhibitory effects on intracellular signaling pathways in thyroid carcinoma cells and caused cell death and cell cycle arrest." (PMID 25879531, 2015).
thyroid cancer (continued). "Twelve thyroid carcinoma cell lines derived from anaplastic, follicular and papillary thyroid carcinomas with wildtype or mutationally activated BRAF were treated with sorafenib." (PMID 25879531, 2015). "The BRAF oncogene is the most frequent genetic alteration in thyroid cancer (i.e., PTC) and is also detected in ATC, associated with poor clinical-pathological features of cancer such as extrathyroidal invasion, short time recurrence, and distant metastases." (PMID 25202329, 2014). "Activation of the MAPK pathway due to gene mutations in RAS and BRAF has been associated with malignant phenotypes in thyroid cancer." (PMID 25295214, 2014). "BRAF V600E mutation is the most common genetic alteration in thyroid cancer, particularly papillary thyroid cancer (PTC; Xing 2005), and plays an important role in thyroid tumorigenesis through aberrantly activating the RAS-BRAF-MEK-MAP kinase (MAPK) pathway." (PMID 24243688, 2014). "Following BRAF mutation, the second most common mutation observed in thyroid cancer are the mutations of RAS proto-oncogenes, which play an important role in the initiation of thyreocyte neoplastic transformation." (PMID 24987460, 2014). "As a potential therapeutic target, the BRAF mutation plays a central role in promoting aggressive phenotype of thyroid cancer and is associated with worse prognosis." (PMID 24673746, 2014). "Recent studies on murine models of BRAF-mutated thyroid cancer demonstrated that BRAFV600E confers the capability to the cells harboring the mutation of potently recruiting macrophages." (PMID 24982657, 2014). "Our data demonstrate that the combined treatment of BRAF mutated thyroid cancer cells with the BRAFV600E-inhibitor PLX4720 and the SRC-inhibitor dasatinib results in a synergistic increase in the anti-proliferative and apoptotic responses in vitro." (PMID 24994118, 2014). "This study supports the application of targeted molecular therapy in thyroid cancer as suggested in earlier studies, by demonstrating that targeting mutated BRAF leads to drastic, selective phenotype changes in thyroid cancer cells in culture." (PMID 24673746, 2014). "We next assessed the usefulness of combined detection of BRAF mutation and methylation markers on FNABs in the diagnosis of malignant thyroid neoplasm." (PMID 24588959, 2014). "For example, BRAF mutations are highly prevalent in thyroid cancer and other cancers, and are associated with more aggressive disease in thyroid cancer." (PMID 25047265, 2014). "Other types of BRAF mutations are rarely described in thyroid cancer: the BRAF V599ins, BRAF V600E+K601del, BRAF K601E, AKAP9-BRAF, and V600D+FGLAT601- 605ins, which result from an insertion of 18 nucleotides at nucleotide T1799." (PMID 24868250, 2013). "BRAF mutations are also highly prevalent in advanced forms of thyroid cancer, and are associated with greater mortality." (PMID 23372702, 2013). "In thyroid carcinomas we also disclosed an association between BRAF mutation and mTOR pathway overactivation." (PMID 23904987, 2013). "The exploration of the relationship between reduced biotinidase, BRAF (V600E) mutation and aggressive thyroid cancers as well as with disease prognosis in larger independent cohorts of this malignancy will constitute the subject of future studies." (PMID 22911723, 2012). "All these mutations potentially lead to upregulation of the RAS/BRAF/mitogen-activated protein kinase (MAPK)/extracellular signal-related kinase (ERK) kinase (MEK)/ERK or MAPK pathway that is involved in thyroid cancer." (PMID 23326755, 2012). "On the other hand, BRAF mutations or RET/PTC rearrangements are commonly seen in thyroid cancer arising in struma ovarii." (PMID 22682753, 2012). "In carcinomas of the thyroid, numerous studies have suggested, although equivocally, that BRAF mutation associates with the older age, advanced disease, classical papillary histology and poorer prognosis as indicated by disease-free and overall survival." (PMID 22682753, 2012).
thyroid cancer (continued). "BRAF V600E can induce thyroid cell transformation in in vitro and thyroid cancer in in vivo, confirming that this mutation is an oncogene for thyroid cancer." (PMID 22654559, 2011). "In human thyroid cancer, BRAF V600E is associated with vascular endothelial growth factor (VEGF) over-expression, which in turn is associated with increasing tumor stage and invasiveness." (PMID 22654559, 2011). "Thyroid cancers with BRAF mutation were preferentially sensitive to MEK inhibitors (PD0325901, AZD6244) whereas tumors with other MEK-ERK effector pathway gene mutations have variable responses." (PMID 20628483, 2010). "BRAF point mutations are less frequent in childhood thyroid cancers, including those children affected by the Chernobyl nuclear calamity." (PMID 21048836, 2010). "Inhibitors of BRAF kinase block the growth of thyroid cancer cells that have RET/PTC or BRAF mutations." (PMID 20628483, 2010). "In thyroid cancer cell lines with RET/PTC or BRAF oncogenic mutations cyclinD1-CDK4 complex is more abundant than cyclinD3-CDK4, suggesting the dominant character of cyclin D1 complexes formation in thyroid oncogenesis." (PMID 19878585, 2009). "In this study we described for the first time, to the best of our knowledge, the effect of both sorafenib and specific siRNA for BRAF in thyroid cancer cells and associated molecules." (PMID 19878585, 2009). "BRAF is frequently subject to point mutations in skin and thyroid cancers (41% and 36%, respectively), but at much lower frequencies in the other tumour types (1–5%)." (PMID 19402918, 2009). "We aimed to characterize in thyroid cancer cell lines with different genetic background those molecules implicated in proliferation/survival using RNAi targeting BRAF and the kinase inhibitor sorafenib." (PMID 19878585, 2009). "In order to fill this lack of knowledge we studied the proliferation and survival pathways and associated molecules induced by BRAF inhibition in thyroid carcinoma cell lines harbouring distinct genetic backgrounds." (PMID 19878585, 2009). "Using thyroid carcinoma cell lines, with different genetic profiles, we characterized the proliferation/survival associated molecules using RNAi targeting BRAF and the kinase inhibitor sorafenib, previously reported to inhibit BRAF." (PMID 19878585, 2009). "Thyroid carcinomas show a high prevalence of mutations in the oncogene BRAF which are inversely associated with RAS or RET/PTC oncogenic activation." (PMID 19878585, 2009). "The thyroid-specific BRAF V600E mouse model also develops invasive and poorly differentiated thyroid cancer that develops progressive local invasion in association with markers of aggressive tumour behaviour." (PMID 17179987, 2007). "Since a BRAF mutation blocks a papillary carcinoma cell from differentiating into follicular cells, a thyroid cancer stem cell with BRAF mutation produces anaplastic carcinoma cells and papillary carcinoma cells, but not follicular carcinoma cells." (PMID 17453004, 2007). "In total, mutations that result in a V600E substitution in BRAF and consequent constitutive activation occur in approximately 45% of PTCs in adults, making BRAF mutations the most common defined genetic abnormality in thyroid cancers." (PMID 17179987, 2007). "The discovery that mutations in BRAF resulting in constitutive kinase activation are common occurrences in solid tumours led a number of groups to analyse thyroid cancers for similar mutations in BRAF." (PMID 17179987, 2007). "The mutation at V600E in the BRAF kinase gene appears to be an attractive molecular marker for thyroid cancer diagnosis as it has been found to be the most common genetic event in PTC, while being highly specific for this tumor." (PMID 16606457, 2006). "However, treatment with BRAF inhibitors paradoxically can enhance FN expression, promoting a more invasive phenotype in BRAF-mutated thyroid cancer cells." (PMID 40423510, 2025).
thyroid cancer (continued). "Similarly, the 8305C cells, derived from anaplastic thyroid carcinoma, also harbor the BRAF mutation, making them a relevant model for the study of aggressive thyroid cancer." (PMID 40004697, 2025). "We statistically analyzed the relationships between recurrence risk, BRAF gene mutation, gender, age at first thyroid cancer diagnosis, tumor size, extrathyroidal invasion, lymph node metastasis, and distant metastasis as well as the expression levels of PROS1, CLU, and LRG1." (PMID 40797389, 2025). "BRAF mutations are the most common genetic alterations in differentiated thyroid cancer." (PMID 40075589, 2025). "Importantly, the BRAF p.V600E variant, as the most extensively studied mutation in thyroid cancer, has been reported to possess an approximate specificity of 100% in PTC." (PMID 40346322, 2025). "Although BCPAP is a classic tool for studying BRAF V600E mutation-positive thyroid cancer, it cannot represent the high heterogeneity of thyroid cancer, including different pathological subtypes (such as follicular carcinoma, anaplastic carcinoma) and individual differences between patients." (PMID 41311976, 2025). "In thyroid cancers, BRAF mutation rates vary across thyroid cancer subtypes." (PMID 40332392, 2025). "The 2022 WHO classification also highlights that RAS-driven tumors, including those with HRASQ61X, tend to behave more aggressively and may require a distinct approach from BRAF-mutated thyroid cancers." (PMID 40104288, 2025). "For instance, genetic markers like BRAF mutations or RET/PTC rearrangements are known to play a critical role in thyroid cancer, and their inclusion could improve the framework’s ability to identify malignancies." (PMID 40989437, 2025). "Univariate binary logistic regression analysis identified age, T stage, N stage, unilateral thyroid involvement, maximum tumor diameter, extra-glandular invasion, and RET, TERT, and BRAF gene mutations as factors significantly associated with lung metastasis in thyroid cancer." (PMID 41306438, 2025). "We identified that PROM1 expression was higher in BRAF-mutated tumors in males within the TCGA Thyroid Cancer database, which may be partly why CD133 expression and prognosis differ in males." (PMID 40214912, 2025). "Therefore, we demonstrated that mannose synergized with PLX4032 to induce apoptosis in BRAF-mutated thyroid cancer cells." (PMID 40063000, 2025). "In PTC, BRAF mutations are the most common molecular alteration, present in 36–69% of cases, and in anaplastic thyroid carcinoma (ATC) in 30–40%, suggesting that BRAF mutated PTCs can progress to less differentiated thyroid cancers (Hsiao & Nikiforov, 2014; Soares & Sobrinho-Simões, 2011)." (PMID 39850836, 2025). "Since BRAF-mutated thyroid cancer highly correlates with the glycolytic metabolic pathway, suppressing glycolysis may enhance the efficacy of PLX4032 in treating ATC." (PMID 40063000, 2025). "BRAF V600E mutations also occur in 40–60% of thyroid cancers." (PMID 40869231, 2025). "The BRAF V600E mutation was first identified in thyroid cancer in 2003, showing a prevalence of approximately 45–50% in papillary thyroid carcinoma (PTC), 25–30% in anaplastic thyroid carcinoma (ATC), and absent in follicular thyroid carcinoma and benign thyroid neoplasms." (PMID 41368991, 2025). "The prevalence of RAS mutations is second only to BRAF mutations in differentiated thyroid cancer." (PMID 40586006, 2025). "BRAF V600E mutations have been well studied and are nearly always associated with thyroid cancer." (PMID 40075589, 2025). "BRAF V600E mutations are nearly always associated with thyroid cancer." (PMID 40075589, 2025). "In addition to its redifferentiation properties, the combination of dabrafenib and trametinib showed intrinsic efficacy in BRAF-mutated thyroid cancers." (PMID 39064466, 2024).